XDH (xanthine dehydrogenase)
Description:
Key enzyme in purine degradation. Catalyzes the oxidation of hypoxanthine to xanthine. Catalyzes the oxidation of xanthine to uric acid. Contributes to the generation of reactive oxygen species. Has also low oxidase activity towards aldehydes (in vitro).
Synonyms: XO; XOR; XDH/XO; XAN1
Tractability: Small molecule: an approved drug acts on it; a structure with a bound ligand is known; a high-quality ligand is known; it has a high-quality binding pocket; it belongs to a druggable protein family. Antibody: UniProt places it where antibodies can reach, with medium confidence; its Gene Ontology location is reachable by antibodies, with medium confidence. PROTAC: a small molecule that binds it is known.
Target class: Enzyme; Oxidoreductase
Chemical probes: PD088612, PD088658, PD088728
Safety:
Unwanted effects reported when the protein is acted on. In parentheses: how it was acted on, where the effect was seen, and who reports it.
noncirrhotic portal hypertension (source: ClinPGx)
Gene: Protein-coding gene on chromosome 2 (31,334,320 to 31,414,747, reverse strand). Ensembl gene ENSG00000158125.
Subcellular location: Cytoplasm; Peroxisome; Secreted
Subcellular location (Human Protein Atlas): Nucleoplasm; Nucleoli
Pathways (Reactome):
Drug ADME: Azathioprine ADME
Immune System: Butyrophilin (BTN) family interactions
Metabolism: Purine catabolism
Gene Ontology:
Molecular function: 2 iron, 2 sulfur cluster binding; flavin adenine dinucleotide binding; hypoxanthine dehydrogenase activity; molybdopterin cofactor binding; protein binding; protein homodimerization activity; xanthine dehydrogenase activity; xanthine oxidase activity; FAD binding; hypoxanthine oxidase activity; iron ion binding; iron-sulfur cluster binding; metal ion binding; oxidoreductase activity
Biological process: allantoin metabolic process; AMP catabolic process; deoxyinosine catabolic process; hypoxanthine catabolic process; IMP catabolic process; inosine catabolic process; xanthine catabolic process; adenosine catabolic process; dAMP catabolic process; deoxyadenosine catabolic process; deoxyguanosine catabolic process; dGMP catabolic process; GMP catabolic process; guanine catabolic process
Cellular component: cytosol; extracellular region; cytoplasm; peroxisome; sarcoplasmic reticulum
Genetic constraint (gnomAD): Loss-of-function variants: 138 observed, 160.62 expected, observed/expected ratio (o/e) 0.86, 90% interval 0.75 to 0.99. The upper end of that interval is the gene's LOEUF score, 0.99, which puts it in group 4 of 6, group 1 being the genes least tolerant of losing a copy. Missense variants: 1,842 observed, 1,751 expected, observed/expected ratio (o/e) 1.05, 90% interval 1.01 to 1.09. Synonymous variants: 665 observed, 650.95 expected, observed/expected ratio (o/e) 1.02, 90% interval 0.96 to 1.09.
Homologues: Orthologues: chimpanzee XDH (99% identical), macaque XDH (97% identical), rabbit XDH (93% identical), dog XDH (90% identical), rat Xdh (90% identical), mouse Xdh (89% identical), pig XDH (89% identical), guinea pig XDH (88% identical), tropical clawed frog xdh (70% identical), zebrafish xdh (68% identical), Drosophila melanogaster ry (53% identical), Caenorhabditis elegans xdh-1 (47% identical). Paralogues in human: AOX1 (50% identical).
Diseases named in the same sentence as XDH in open-access papers:
XDH is named in the same sentence as 350 diseases in open-access papers, as found by Europe PMC text mining. Sharing a sentence is not in itself a finding about the gene and the disease. The quoted sentences say what the papers report.
hyperuricemia (451 papers, 2004 to 2026). An abnormally high level of uric acid. "Both ABCG2 and XDH inhibition have been associated with hyperuricemia and gout, providing further evidence of our hypothesis that these proteins act in the same pathway." (PMID 37218814, 2023). "Treatment with AICAR in vivo increases purine degradation and production of uric acid, leading to hyperuricemia, which can be prevented by inhibiting xanthine dehydrogenase with allopurinol." (PMID 40793247, 2025). "The secretion level of XDH is basically positively correlated with the abundance of Escherichia-Shigella, which can convert the purine in hyperuricemia mice into UA." (PMID 38674582, 2024). "The effects of GalNAc-siRNAs were evaluated in three hyperuricemia mouse models, including potassium oxonate and hypoxanthine administration in WT and humanized XDH mice and Uox knockout mice." (PMID 39065635, 2024). "XDH (XOR), the rate-limiting enzyme produced by SUA, is not only highly expressed in hyperuricemia and gout but has also been shown to have significantly higher XOR activity in diabetic patients than in normal adults." (PMID 37955008, 2023). "Another drug, febuxostat, also targets xanthine dehydrogenase and is approved for the management of chronic hyperuricemia in cases where there is an inadequate response or intolerance to allopurinol." (PMID 35454087, 2022). "The xanthine oxidase activity and xanthine dehydrogenase mRNA expression in the liver were significantly increased in the hyperuricemia-induced mice group compared with those in the normal control group." (PMID 34451714, 2021). "FSU-CC 300 supplementation significantly decreased the xanthine oxidase activity and xanthine dehydrogenase mRNA expression in the liver of hyperuricemia-induced mice more than the individual supplementation of either Ci 300 or Co 300 alone (p < 0.05)." (PMID 34451714, 2021). "We measured the xanthine oxidase activity, xanthine dehydrogenase mRNA expression, and oxidative stress in the liver of hyperuricemia-induced mice." (PMID 34451714, 2021). "In the present study, quercetin was confirmed to prevent the conversion of renal XDH to XO, which were consistent with its attenuation of Cd-induced hyperuricemia and renal injury." (PMID 22690247, 2012). "However, Ci 300 and Co 300 supplementation suppressed the xanthine oxidase activity and xanthine dehydrogenase mRNA expression in the liver of hyperuricemia-induced mice." (PMID 34451714, 2021). "Such research will shed light on the roles of homologous genes in humans with metabolic conditions as hyperuricemia and gout and on the effects of drugs used to treat these conditions, such as the xanthine dehydrogenase inhibitor drug allopurinol, which is widely used to prevent UA production." (PMID 34571893, 2021). "In the present, we analyze the bacteria targeted by ingredients of CoTOL and evaluate the effects of CoTOL on uric acid and intestinal flora in a mice model of obese hyperuricemia inoculated with xanthine dehydrogenase- (XOD-) producing bacteria, Streptococcus faecalis." (PMID 33424995, 2020). "In addition, zinc improved the efficacy of uric acid reduction by suppressing xanthine oxidase/xanthine dehydrogenase (XOD/XDH) in a hyperuricemia mouse model." (PMID 30400133, 2018). "B. xylanisolvens reduces serum uric acid concentrations in hyperuricemia in the Goslings' model, and it can up-regulation ABCG2 mRNA expression in the kidney and down-regulation XDH mRNA expression in the liver." (PMID 37455728, 2023). "We found that our newly isolated Bacteroides xylanisolvens could inhibit hyperuricemia in goslings by up-regulating ABCG2 mRNA expression in the kidney and down-regulating XDH mRNA expression in the liver." (PMID 37455728, 2023).
hyperuricemia (continued). "Regulation of uric acid oxidase (uricase), xanthine oxidase (XO), and xanthine dehydrogenase (XDH) activities by different bacterial strains also impair purine absorption and alter the balance of the intestinal flora, which can attenuate or exacerbate hyperuricemia." (PMID 40161295, 2025). "To search for these natural products, we first used the following key words in PubMed: “uric acid” or “hyperuricemia” or “gout” and “medicinal plant” or “herb” or “herbal medicine” or “natural products” or “phytomedicine” or “phytotherapy” and “xanthine oxidase” or “XOD” or “XDH”." (PMID 27847526, 2016).
gout (339 papers, 2012 to 2026). A condition characterized by painful swelling of the joints, which is caused by deposition of urate crystals. "In conclusion, this drug-target MR study demonstrated that XDH-variant-induced reductions in serum uric acid were significantly associated with reduced risks of cerebral infarction and gout." (PMID 38228698, 2024). "In this study, the XDH-variant-induced reduction in serum uric acid was associated with reduced cerebral infarction and gout risks." (PMID 38228698, 2024). "We included 474,983 non-gout individuals with XDH-associated single-nucleotide polymorphisms." (PMID 38228698, 2024). "A one-unit decrease in the scaled serum uric acid levels related to the selected XDH variants was associated with a 15% reduction in the odds of gout (odds ratio [OR], 0.85; 95% confidence interval [CI], 0.78–0.93; P < 0.001) and cerebral infarction (OR, 0.86; 95% CI, 0.75–0.98; P = 0.023)." (PMID 38228698, 2024). "In gout, dysregulation of the uric acid cycle can negatively impact the liver, as it is a major site of purine metabolism, where xanthine oxidoreductase (XDH) converts hypoxanthine and xanthine into uric acid." (PMID 41583461, 2025). "The effect of uric acid reduction on gout mediated by XDH-inhibition was maintained following stratification by lipid level." (PMID 38228698, 2024). "Accordingly, we observed a negative association with serum urate (beta = −0.04, p = 2.0 × 10−11) and a protective effect on gout (gout OR = 0.8, beta = −0.22, p = 0.16), consistent with the effectiveness of XDH inhibitors for urate-lowering treatment." (PMID 36890159, 2023). "As XDH inhibitors have been used for the therapy of gout for a long time, it is worthwhile to for further investigate the efficacy of XDH inhibitors in combination of drugs inducing UPR/autophagy." (PMID 36778128, 2023). "Allopurinol, an FDA-approved drug that inhibits xanthine oxidase and xanthine dehydrogenase, has been used in clinic for the treatment of gout." (PMID 37752569, 2023). "The most consistent inverse association across both studies and all three neurodegenerative diseases was for xanthine dehydrogenase/oxidase blockers, represented by the gout medication, allopurinol." (PMID 37195983, 2023). "We have elucidated the enrichment of three bacterial xanthine dehydrogenase isoforms with oxidoreductase activity in tophaceous gout patients." (PMID 34030623, 2021). "In patients with gout, microbiota with the xanthine dehydrogenase gene are enriched whereas microbiota with the allantoinase gene, which degraded uric acid to urea, are depleted." (PMID 33329010, 2020). "On the pathway of purine metabolism, the xanthine dehydrogenase which can degrade the purine to uric acid was enriched in the gout patients, whereas the allantoinase that degrades the uric acid to urea was depleted." (PMID 26852926, 2016). "On the other hand, the microbial xanthine dehydrogenase which can degrade the purine to uric acid was enriched in the gout patients whereas the microbial allantoinase that degrades the uric acid to the urea was depleted in gut patients." (PMID 26852926, 2016). "We hypothesized that the increased activity of xanthine dehydrogenase and the enzymes of ureide synthesis in tophaceous gout patients is likely an adaptive process of the gut microbiome, which may be attributable to more than 8 years of allopurinol treatment." (PMID 34030623, 2021). "The high potency of leaf and barkextracts of F. angustifolia against the NADH oxidaseactivity of xanthine dehydrogenase both in vitro and in vivoprovides strong evidence for the use of this plant to fightantiinflammatory disorders, particularly gouty arthritis." (PMID 31410081, 2019). "A recent genome-wide association study of over 2.6 million individuals identified XDH activity in the prostate in the progression from HU to gout, but whether the human prostate produces urate and to what extent it has an effect on whole-body blood urate levels remain to be determined." (PMID 39872146, 2024).
gout (continued). "Xanthine dehydrogenase (XDH) and hypoxanthine-guanine phosphoribosyltransferase (HPRT) emerge as two promising therapeutic targets for gout." (PMID 40077420, 2025). "Febuxostat, as a potent inhibitor against XDH, which has been widely used in clinical practice, has a good curative effect on patients with HUA or gout." (PMID 38435751, 2024). "Analysis of the functional feature as defined by COGs revealed that the xanthine dehydrogenase (COG4360 and COG4361) was significantly enriched (P < 0.05, Wilcoxon rank-sum test) in gout patients, but the allantoicase (COG4266) depleted." (PMID 26852926, 2016). "Our findings showed that xanthine stimulation upregulated XDH and pro-inflammatory cytokines, whereas IRAK4 inhibitor treatment significantly suppressed both XDH expression and cytokine production, indicating that IRAK4 signaling may also contribute to liver inflammation in the context of gout." (PMID 40709261, 2025).
endothelial dysfunction (118 papers, 2005 to 2026). In vascular diseases, endothelial dysfunction is a systemic pathological state of the endothelium (the inner lining of blood vessels) and can be broadly defined as an imbalance between vasodilating and vasoconstricting substances produced by (or acting on) the endothelium. "We also found dysregulation of angiogenesis genes (XDH, SEMA5A, and SULF1) and the Rap1 pathway (ADORA2B, GNAO1, SULF1, and EFNA2), which promotes endothelial homeostasis and may be involved in endothelial dysfunction-associated cardiovascular pathologies." (PMID 38255763, 2024). "Moreover, XDH switches to XO when released to the blood circulation, leading to further ROS generation and endothelial dysfunction by binding XO with sulfated glycosaminoglycans." (PMID 35370681, 2022). "Compelling evidence suggests that the cellular ratio of XO to XDH is critical to the development of atherosclerosis, endothelial dysfunction, nephro-vascular hypertension and cardiovascular disease in general." (PMID 28914782, 2017).
Hypertension (85 papers, 2009 to 2025). The presence of chronic increased pressure in the systemic arterial system. "Reactive oxygen species are produced as xanthine dehydrogenase/xanthine oxidase (XDH/XO) catabolizes the formation of uric acid, increasing the risk of high blood pressure, elevated cholesterol levels, diabetes, and atherosclerosis." (PMID 40104211, 2025). "Initial association studies within a cohort of 1818 Japanese individuals highlighted several XDH SNPs linked to hypertension, showing distinctions between males and females." (PMID 39765766, 2024). "In a European case-control cohort comprised of 185 hypertensive patients and 385 controls, two XDH SNPs (-337GA, rs206812; and 565 + 64CT, rs2073316) were examined for their association with hypertension." (PMID 39765766, 2024). "While clinical studies link UA to hypertension and other cardiovascular risks, the biochemical implications of specific XDH mutations on these mechanisms are underexplored." (PMID 39765766, 2024). "XDH variants have been associated with xanthinuria, and recently with systemic hypertension and oxidative stress." (PMID 37415141, 2023). "We aimed to examine the association of sUA concentration on the risk of hypertension in pre- and post-menopausal women and investigated the association between the polymorphism of the xanthine dehydrogenase gene and the risk of hypertension." (PMID 31126092, 2019). "We found that participants with XDH rs206847 CC genotype had a risk of hypertension with statistical significance (OR=3.63)." (PMID 31126092, 2019). "We examined the association between sUA and hypertension risk in post-menopausal women, and investigated the association between the polymorphism of XDH gene and the risk of hypertension." (PMID 31126092, 2019). "In order to investigate an association between genetic variants in XDH and risk of hypertension, we examined confounding factors in multivariate logistic regression analysis gradually." (PMID 31126092, 2019). "Other SNPs of XDH gene associated with hypertension were also reported." (PMID 31126092, 2019). "This study suggests that sUA concentrations might be associated with an increased risk of hypertension in postmenopausal women and that the rs206860 polymorphism of the XDH gene might be associated with a low risk of hypertension in Koreans." (PMID 31126092, 2019). "Furthermore, XDH rs206860 AG genotype was found to be associated with the decreased risk of hypertension." (PMID 31126092, 2019). "In addition, we investigated an association between xanthine dehydrogenase gene and sUA and their combined associations on the risk of hypertension." (PMID 31126092, 2019). "Interestingly, we found genetic variations of the rs206860 polymorphism of XDH gene might lower the risk of hypertension." (PMID 31126092, 2019). "There is evidence linking XDH mutations with the development and progression of CVD risk factors in Japanese cohorts, including hypertension, atherosclerosis, and chronic kidney disease (CKD)." (PMID 39765766, 2024). "Some studies have suggested that XDH activity is enhanced in patients with hypertension and a higher production of H2O2 mediated by XDH in hypertensives as compared with controls has been described." (PMID 38983269, 2024). "As far as we know, XDH rs206860 and its associations with hypertension have not been studied." (PMID 31126092, 2019). "While XDH prefers NAD+ as an electron acceptor, XO transfers the electrons directly to molecular oxygen, resulting in the production of ROS4,6,20, i.e., superoxide anion and hydrogen peroxide, which have been implicated in the development of hypertension, dyslipidemia, and diabetes." (PMID 29133805, 2017).
atherosclerosis (71 papers, 2004 to 2025). A disease characterized by the build-up of fatty material and calcium deposition in the arterial wall resulting in partial or complete occlusion of the arterial lumen. "In humans, xanthine and xanthine dehydrogenase are linked to both atherosclerosis and urinary stones, two forms of ectopic calcification." (PMID 25970330, 2015). "Oscillatory shear stress increases endothelial XOR expression and activity, activates nicotinamide adenine dinucleotide phosphate (NADPH) oxidase, and significantly increases ROS production by promoting the conversion of XDH to XO, thereby promoting atherosclerosis." (PMID 36979733, 2023).
Obesity (64 papers, 2004 to 2025). Accumulation of substantial excess body fat. "Indeed, it is recently been shown that the serum level of xanthine dehydrogenase is correlated with obesity-related metabolic indexes in blood such as triglycerides, cholesterol, and glucose." (PMID 31311600, 2019).
heart failure (62 papers, 2009 to 2025). Inability of the heart to pump blood at an adequate rate to meet tissue metabolic requirements. "These four genes CAMTA2, ITGB6, NFATc2, and XDH are all related to heart failure, fibrosis, and cardiovascular disease." (PMID 40181955, 2025).